EGFR (epidermal growth factor receptor)
Diseases named in the same sentence as EGFR in open-access papers (continued):
Sharing a sentence is not in itself a finding about the gene and the disease.
colorectal cancer (continued). "The efforts to develop targeted drugs for treating colorectal cancer are increasing, however, the candidates of target drugs other signaling pathways besides EGFR and mismatch Repair are limited." (PMID 36129915, 2022). "A pre-clinical trial of Anti-EGFR antibody cetuximab (C255) approved by FDA for the treatment of EGFR – positive colorectal cancer and palladium compound (TOOKAD) is a clinical trial by photo-dynamic therapy for the treatment of prostate cancer." (PMID 35425710, 2022). "OGN has the ability to reduce proliferation and invasion of colorectal cancer cells by binding EGFR and promoting its internalization, resulting in the impairment of pro-mitotic signaling and EMT driven by the EGFR/AKT/Zeb-1 axis." (PMID 35454809, 2022). "Cetuximab is a chimeric mouse-human monoclonal antibody biologic used for the treatment of epidermal growth factor receptor-positive colorectal cancer and head and neck cancer." (PMID 35903575, 2022). "In particular the genetic heterogeneity of colorectal cancer along with the dynamic nature of tumor biology are at the basis of secondary resistance to EGFR blockade." (PMID 35530345, 2022). "We find that, ARID1A and EGFR-pathway genetic alterations are mutually exclusive across lung and colorectal cancers, further supporting a functional connection between these pathways." (PMID 36117191, 2022). "We apply our novel scores to quantify the spatial expression of four different membrane markers, i.e., HER2, CMET, CD44, and EGFR in immunohistochemically (IHC) stained tissue sections of colorectal cancer patients." (PMID 36601480, 2022). "Combined with the protein targets screened in the previous network pharmacology, we suppose miR-145 suppresses tumorigenesis and metastasis of the colorectal cancer cells by inhibiting the expression of EGFR." (PMID 35847793, 2022). "In this study, nude mice bearing human colorectal cancer cells were treated with the standard chemotherapeutic 5-fluorouracil (5-FU) and subsequently evaluated with molecular endoscopy for EGFR expression." (PMID 35280747, 2022). "In summary, heteronemin induced anti-proliferation in colorectal cancer cells by blocking the EGFR-dependent signal transduction pathway." (PMID 36005485, 2022). "In recent years, the emergence of molecular targeted drugs like the EGFR (Epidermal Growth Factor Receptor) monoclonal antibody has shown obvious curative effects in patients with terminal colorectal cancer." (PMID 36258178, 2022). "With regard to the gastrointestinal digestive system, colorectal cancer escapes EGFR blockade by downstream signaling activation (RAS-MEK), and combination of EGFR blockade and MEK blockade can prevent resistance both in vitro and in vivo." (PMID 35903676, 2022). "For patients with metastatic RAS/RAF wild-type refractory colorectal cancer, the question of anti-EGFR therapy rechallenge often comes up after initial use." (PMID 35837097, 2022). "In conclusion, Ephexin1 is proposed as an effective target protein for the therapy of tumors in lung and colorectal cancers since it plays an important role in regulating interactions between EGFR and EphA2." (PMID 35668076, 2022). "By examining the important signaling molecules linked to EGFR and PD-L1, results showed that PSP treatment significantly reduced the expression levels of p-EGFR(Tyr1068), c-Jun, STAT3, and p-STAT3(Tyr705) in colorectal cancer cells." (PMID 36359361, 2022). "Paired primary tumors and lymph node metastases from 79 patients with colorectal cancer were retrospectively collected and analyzed for EGFR, HER2, and HER3 expression." (PMID 35902718, 2022). "For this reason, EGFR inhibitors such as cetuximab can play an important role in treating cancers such as colorectal cancer and head and neck cancer." (PMID 35076451, 2022). "EGFR copy number gain ≥4.0/nucleus confers significantly improved PFS with anti-EGFR therapy (HR 0.2, 95% CI: 0.1–0.5) in colorectal cancer patients refractory to chemotherapy." (PMID 35565354, 2022).
colorectal cancer (continued). "Previous studies of ctDNA in colorectal cancer patients have demonstrated a positive selection of mutant KRAS clones during epidermal growth factor receptor (EGFR) blockade, and a decline in mutant KRAS clones upon the withdrawal of the therapy." (PMID 35273301, 2022). "The role of miR-31-3p was evaluated in multiple studies dealing with the monitoring of anti-EGFR therapy in patients with colorectal cancer." (PMID 35457163, 2022). "A recent study has demonstrated that EGFR/STAT/ERK pathway is involved in the anti-cancer activities of 8GL in colorectal cancer in vitro." (PMID 36437247, 2022). "Other than TAT, Cetuximab (CTX, a monoclonal anti body (mAb) against epidermal growth factor receptor (EGFR)) was also used to target PEGylated liposomes loaded with Oxaliplatin at EGFR-expressing colorectal cancer." (PMID 36297598, 2022). "Epidermal growth factor receptor (EGFR) is among the most prominent targets in colorectal cancers (CRCs) treatments." (PMID 35918704, 2022). "Abnormal and uncontrolled activation of the EGFR pathway correlates with lung and colorectal cancer progression, and EphA receptor overexpression promotes cancer malignancy." (PMID 35668076, 2022). "A study showed that in colorectal cancer, EGFR protein overexpressed from 25% to 82% and one available drug was in the phase II clinical stage to treat patient." (PMID 36457709, 2022). "The tumor group showed similar expression of the highly expressed oncogenes in colorectal cancer, including previously reported EGFR and ERBB2, and the solute carrier (SLC) family." (PMID 36459282, 2022). "Increased MACC1 expression also leads to EGFR and its mediated downstream signaling pathway activation and cell proliferation, promoting the progression of colorectal cancer." (PMID 35242498, 2022). "In current clinical practice, anti-EGFR mAb is only approved for patients with RAS wild-type colorectal cancer." (PMID 35433839, 2022). "Cetuximab (EGFR monoclonal antibody) is FDA‐approved for EGFR‐expressing tumors in head‐and‐neck cancer and colorectal cancer." (PMID 35229492, 2022). "Cetuximab (Erbitux) is an anti-EGFR monoclonal antibody clinically approved for treating colorectal cancer." (PMID 36230087, 2022). "For example, male or young patients with colorectal cancer (CRC) treated with cetuximab, an anti-EGFR antibody drug, are at an increased risk of developing grade 2–3 acneiform rash." (PMID 36045384, 2022). "In this research project, we evaluated the immunomodulatory effects of MSC-derived exosomes, as well as MSC’s conditioned media, on AQP5 and EGFR gene expression in a highly invasive colorectal cancer cell line “HCT-116”." (PMID 36114463, 2022). "Together, these results suggest a link between lung and colorectal cancers and the expression of Ephexin1, EphA2 and EGFR, and the possibility that these proteins interact with each other, either directly or indirectly." (PMID 35668076, 2022). "One of the main focuses of targeted treatments in colorectal cancer is EGFR, which upon homo- or hetero-dimerization with another RTK to activate downstream signaling pathways." (PMID 36551663, 2022). "Taken together, these findings suggested that REG4 is a potent activator of the EGFR/Akt pathway for the proliferation and anti-apoptosis of colorectal cancer cells." (PMID 36172286, 2022). "Overexpressed EGFR and mutant K-Ras play vital roles in therapeutic resistance in colorectal cancer patients." (PMID 36005485, 2022). "Since cancer cells rely on these pathways, EGFR is a useful target in the therapy of colorectal cancer metastases." (PMID 35455247, 2022). "The present study demonstrated that CB1 activation suppressed M2 macrophage through EGFR downregulation in colorectal cancers." (PMID 35641479, 2022). "Because it is prevalent in a wide range of solid tumors, including colorectal cancer, epidermal growth factor receptor (EGFR) is a major cancer therapeutic target." (PMID 35530318, 2022).
colorectal cancer (continued). "We also evaluated the potential for the simultaneous use of 89Zr-matuzumab PET/CT and nimotuzumab-PEG6-DM1 for biparatopic imaging and therapy, respectively, in EGFR-positive KRAS mutant colorectal cancer models." (PMID 36145664, 2022). "In light of this, we further investigated the possible role played by EPLIN and HSP60 in the responsiveness of colorectal cancer cells to chemotherapeutic and EGFR/Her2 targeted therapeutic agents." (PMID 36499558, 2022). "In the present study, we explored the rechallenge strategy with cetuximab-based therapy in clinically and molecularly selected, heavily pretreated (i.e., 92.3% received rechallenge with anti-EGFR in fourth- or fifth-line therapy) colorectal cancer patients." (PMID 35530345, 2022). "Similar observations on the presence of KRAS mutation and sensitivity to cetuximab (monoclonal antibody against epidermal growth factor receptor EGFR) in colorectal cancer have already been implemented into clinical practice." (PMID 35206475, 2022). "Clinical research data also support the application of anti-EGFR mAb in patients with advanced colorectal cancer." (PMID 35433839, 2022). "BRAF mutations are targeted currently in colorectal cancer in the clinic at the second line metastatic setting with a regimen that combines BRAF inhibitors and anti-EGFR monoclonal antibodies." (PMID 36295658, 2022). "We previously showed that miR-100 and miR-125b, embedded within the third intron of the ncRNA host gene MIR100HG, confer resistance to cetuximab, an anti-epidermal growth factor receptor (EGFR) monoclonal antibody, in colorectal cancer (CRC)." (PMID 35279145, 2022). "Contrary to these conclusions however, an exon II-dependent mechanism of AURKA translational activation was proposed for colorectal cancers in which both EGFR and AURKA are overexpressed." (PMID 36067794, 2022). "Activation of MOR by morphine promotes proliferation, invasion, and migration of human colorectal cancer cells, which is possibly due to transactivation of epidermal growth factor receptor (EGFR) and downstream signaling pathways." (PMID 36118524, 2022). "Colorectal cancer cells show increased basal phosphorylation of EGFR and respond to EGF by activating MAPK signaling, even in the presence of an activating KRAS G12C mutation that is not observed in NSCLC cells." (PMID 35267628, 2022). "As a result, this study is expected to provide an opportunity to try a wider range of therapeutics in colorectal cancer, where EGFR inhibitors and ICI are limitedly used as targeted therapeutics." (PMID 36129915, 2022). "As a protein tyrosine kinase, epidermal growth factor receptor (EGFR) is overexpressed in colorectal cancer." (PMID 36080457, 2022). "Recently, the Tz/TCO-based and cetuximab pretargeted imaging strategy was successfully used for assessing the EGFR expression in colorectal cancer." (PMID 35903247, 2022). "As in thyroid cancers, NRG1-induced HER3 activation plays an important role in adaptive resistance to RAF or MEK inhibitors in melanomas, whereas EGFR plays a more critical role in colorectal cancers." (PMID 36476495, 2022). "Collectively, this indicates that EPLIN and HSP60 have the potential to regulate colorectal cancer cell’s response to both chemotherapeutic and EGFR/Her2 targeted therapeutic agents." (PMID 36499558, 2022). "EGFR therapy in colorectal cancer” has been cited 1238 times since its publication and is the most frequently quoted research about drug resistance and CRC." (PMID 36110958, 2022). "To specifically target “undruggable” oncogenes, we initially invented an RNAi-based targeted therapy option that uses the internalization capacity of a colorectal cancer specific anti-EGFR-antibody bound to cationic protamine and the anionic siRNA." (PMID 36457063, 2022). "This retrospective study included 67 patients with unresectable advanced or recurrent colorectal cancer treated with anti-EGFR antibody drugs for the first time." (PMID 36045384, 2022).
colorectal cancer (continued). "Our results also showed that EGFR was overexpressed in colorectal cancer cells, which is consistent with the fact that EGFR overexpression has been observed in about 70% colorectal cancer patients." (PMID 35641479, 2022). "Not only that, we also identified EGFR and its signalling pathway, and anti-EGFR drugs (cetuximab or panitumumab) are commonly used clinically for the treatment of colorectal cancer." (PMID 35814224, 2022). "A number of studies have established that EGFR was crucial for the development of colorectal cancer." (PMID 35641479, 2022). "This bypass mechanism is essential for colorectal cancer cells to develop resistance to EGFR-targeted therapy." (PMID 35903358, 2022). "In the present study, we found that the expression of EGFR, EphA2, and Ephexin1 was upregulated and correlated to lung and colorectal cancers." (PMID 35668076, 2022). "In colorectal cancer cells, ginsenoside Rd, a therapeutic agent, targets epidermal growth factor receptor (EGFR)/SOX2 signaling." (PMID 35928281, 2022). "We detect the receptor tyrosine kinase activity in gefitinib-resistant colorectal cancer cells, ErbB3/EGFR is significantly activated and provides a potential multi-ErbB treatment target." (PMID 35319011, 2022). "In clinical practice, EGFR-targeted therapy (cetuximab) can improve the overall survival (OS) in KRAS wild type colorectal cancer patients, which is an important method of targeted therapy for colorectal cancer patients." (PMID 35319011, 2022). "Taken together, these results demonstrated that CB1 was lower expressed while EGFR was higher expressed in colorectal cancer cells." (PMID 35641479, 2022). "Our study aimed to prepare EGFR-targeted DSPE-PEG2000 liposomes as CPT-11 delivery systems for colorectal cancer therapy." (PMID 35918704, 2022). "In 65–75% patients with advanced colorectal cancer, EGFR is overexpressed, and EGFR-targeting therapies, such as cetuximab, have improved outcomes for colorectal cancer patients." (PMID 35641479, 2022). "The presence of inactivating mutations in RNF43, a negative regulator of WNT, in tumor cells predicts improved response rates and survival outcomes in patients with metastatic BRAFV600E colorectal cancer treated with anti-BRAF/EGFR therapy." (PMID 36097219, 2022). "Although approximately 80% of colorectal cancer patients have EGFR-expressing tumors, the level of EGFR expression can differ between tumors." (PMID 35035479, 2022). "Antibodies against EGFR and small-molecule kinase inhibitors are both used to treat various cancers, including lung and colorectal cancer." (PMID 35804847, 2022). "This receptor is known to play a key role in various cancers, including non-small-cell lung, breast, and colorectal cancer, which led to the approval of both small-molecule tyrosine kinase inhibitors and antibodies targeting EGFR." (PMID 35804847, 2022). "Anti-EGFR immunoPET using cetuximab and panitumumab showed specific but heterogeneous uptake in EGFR-expressing preclinical models and colorectal cancer patients." (PMID 35836956, 2022). "Anti-BRAF/EGFR therapy was recently approved for the treatment of metastatic BRAFV600E colorectal cancer (mCRCBRAF-V600E)." (PMID 36097219, 2022). "Western blot results further validated the downregulation of CB1 and the upregulation of EGFR in colorectal cancer cells." (PMID 35641479, 2022). "For example, panitumumab (Vectibix), a fully human Ab directed against EGFR, is used to treat advanced colorectal cancer." (PMID 35101043, 2022). "In colorectal cancer patients with different KRAS mutations, KRASG13D shows some sensitivity to anti-EGFR cetuximab, albeit less than wild-type did." (PMID 36145664, 2022). "In colorectal cancer, the response of EGFR to treatment with cetuximab is dependent on PTEN status, and in PC-3 cells, restoration of PTEN expression improved response to cetuximab-induced apoptosis and the inhibition of cell proliferation." (PMID 35804847, 2022).
colorectal cancer (continued). "Metastatic colorectal cancer patients amenable for anti-EGFR mAb treatment currently receive relatively high doses (250–500 mg/m2 of cetuximab or 6 mg/kg of panitumumab), which is aimed to block EGF binding to EGFR." (PMID 35035479, 2022). "This inhibitor shows potent antitumor activity in several preclinical models of pancreatic and colorectal cancer, especially when combined either with cetuximab, a monoclonal antibody against the EGFR, or with BYL‐719, a potent PI3Kα inhibitor." (PMID 36383067, 2022). "HT-29 cells overexpress EGFR and are representative of wildtype-KRAS and BRAF-mutated tumours, which have been reported in approximately 5-15% of patients with colorectal cancers." (PMID 36591314, 2022). "Compared with FHC cells, the mRNA levels of CB1 were downregulated in colorectal cancer cells, while the mRNA levels of EGFR were upregulated in colorectal cancer cells." (PMID 35641479, 2022). "This study aimed to develop the CPT-11-loaded DSPE-PEG 2000 targeting EGFR liposomal delivery system and characterize its targeting specificity and therapeutic effect on colorectal cancer (CRC) cells in vitro and in vivo." (PMID 35918704, 2022). "In conclusion, our study showed that CB1 activation suppressed tumor growth and M2 macrophage activation in colorectal cancer by downregulating EGFR." (PMID 35641479, 2022). "The epidermal growth factor receptor (EGFR) signaling pathway is commonly activated in colorectal cancer." (PMID 36103569, 2022). "The epidermal growth factor receptor (EGFR) is a major therapeutic target in colorectal cancers, and the KRAS mutation test is essential in clinical practice for predicting resistance to EGFR inhibitors during metastatic colorectal cancer treatment." (PMID 36083889, 2022). "In colorectal cancer, EGFR S468R substitution induces cetuximab resistance; however, the newer-generation anti-EGFR antibody necitumumab can overcome this resistance and inhibit altered EGFR." (PMID 35626010, 2022). "The aim of the present study was to determine the effect of cell-penetrable nanobody (R9VH36) on cell viability and proteomic profile in EGFR-positive human colorectal cancer cell lines." (PMID 35578244, 2022). "Since these pathways are essential for the survival of cancer cells, EGFR is a valuable target in the treatment of colorectal carcinoma metastases." (PMID 35455247, 2022). "The colorectal carcinoma cell line RKO had about 10 times less EGFR expression, whereas the colorectal carcinoma cell line SW620 hardly expressed EGFR." (PMID 35035479, 2022). "In patients with colorectal carcinoma metastasis, KRAS and NRAS mutations are tested prior to anti-epidermal growth receptor (EGFR) target therapy, as mutated RAS proteins downstream of EGFR will impair treatment effectiveness." (PMID 35328664, 2022). "On account of its major and diverse roles in cancer, it is important to target EGFR in particular for better tumor selection, as EGFR is overexpressed in 25 to 82% of colorectal carcinoma cases." (PMID 35455247, 2022). "Altogether, our findings reveal that PRMT5 controls EMT through activation of the EGFR/Akt/GSK3β signaling pathway in colorectal cancer cells." (PMID 33495409, 2021). "In colorectal cancer, most biological drugs that are used target the epidermal growth factor receptor (EGFR), which mediates cellular response to growth signals and is known to be over-expressed in 50–80% of colorectal tumors." (PMID 33669856, 2021). "PRMT1-mediated H4R3me2a recruits SMARCA4, which promotes colorectal cancer progression by enhancing EGFR signaling." (PMID 33853662, 2021). "Epidermal growth factor receptor (EGFR), a member of the subclass I of the receptor tyrosine kinase super-family, is overexpressed in 49% to 82% of colorectal cancer 14-16." (PMID 33758598, 2021).